JAK2 (Janus kinase 2)
Diseases named in the same sentence as JAK2 in open-access papers (continued):
Sharing a sentence is not in itself a finding about the gene and the disease.
polycythemia vera (continued). "Polycythemia vera is rarely reported in animals, even though, a genetic mutation in JAK2 has been identified in dogs." (PMID 33622355, 2021). "In humans, polycythemia vera is due to the mutation (V1617F) in the pseudokinase domain of Janus-activated kinase 2 (JAK2)." (PMID 33622355, 2021). "Somatic variant p.Val617Phe and variants in exon 12 of the JAK2 gene are the reason for the development of somatic erythrocytosis also termed polycythemia vera (PV) (OMIM ID: 263300) in 98% of erythrocytosis cases." (PMID 34349782, 2021). "The WHO classification system for MPNs includes seven subcategories, but more commonly this refers to the JAK2 mutation-enriched diseases polycythaemia vera (PV), essential thrombocythaemia (ET) and primary myelofibrosis (PMF)." (PMID 34778087, 2021). "Almost all patients with polycythemia vera have a gain-of-function mutation in the Janus kinase 2 gene (JAK2) with the resultant constitutively activated JAK/STAT signaling pathway causing the MPN phenotype." (PMID 31065022, 2019). "An activating mutation in JAK2 (V617F) is present in ~ 95% of polycythemia vera, essential thrombocythemia, and primary myelofibrosis cases." (PMID 30717771, 2019). "JAK2 V617F (Val617Phe) G>T mutation, was recently described in most patients with polycythemia Vera (PV) and in essential thrombocythemia (ET) and mutation of both JAK2 alleles has been reported in approximately 100% of the PV patients." (PMID 31870101, 2019). "Mutations in JAK2 leading to constitutive activation of the JAK-STAT pathway are common in polycythemia vera." (PMID 31781977, 2019). "The BCR-ABL negative MPNs, frequently characterized by mutations in Janus kinase 2 (JAK2), are further subclassified into essential thrombocythemia (ET), polycythemia vera (PV), primary myelofibrosis (PMF), and unclassifiable MPN." (PMID 31126326, 2019). "Ruxolitinib—a potent JAK1/JAK2 inhibitor—is approved to treat hydroxyurea intolerant/refractory PV, high-risk myelofibrosis (MF) which includes: primary MF, post–polycythemia vera MF and post-essential thrombocythemia MF." (PMID 29382159, 2018). "This is especially true for JAK2 activation mutation, where the most frequent mutation V617F is seen in over 95% of cases of polycythemia vera and up to 57% in patients with primary myelofibrosis or essential thrombocythemia." (PMID 29862290, 2018). "Most cases of polycythemia vera are due to gain-of-function JAK2 (Janus Kinase 2; 9p24) somatic mutations, over 95% of which are located in exon 14 (JAK2V617F)." (PMID 29534684, 2018). "A diagnosis of polycythemia vera (PV) with JAK2 V617F mutation was made at age 47, and aspirin therapy was initiated." (PMID 30225530, 2018). "Here we describe the clinical presentation and brain magnetic resonance imaging (MRI) findings of a patient with HE and discovery of PVT, the etiology of probably attributed to polycythemia vera with Janus kinase 2 (JAK2) gene mutation." (PMID 28540277, 2017). "The result of the test for JAK2-V617F gene mutation was positive, suggesting the presence of polycythemia vera." (PMID 28540277, 2017). "How TPO-R interacts with JAK2 is particularly relevant in the context of disease driven by mutations in JAK2, specifically JAK2 V617F, which occurs in about half of patients with ET and MF, and most patients with polycythemia vera." (PMID 28408900, 2017). "In contrast to JAK2 mutations being mainly associated with polycythaemia vera, CALR mutations are only associated with primary myelofibrosis (PMF) and essential thrombocythaemia (ET)." (PMID 26202929, 2016). "Polycythaemia vera is associated with JAK2 mutations (JAK2 V617F and JAK2 exon 12 mutations) in virtually all cases." (PMID 26202929, 2016). "JAK2 mutations affecting the JAK-STAT signal transduction pathway are found in 90%-95% of patients with polycythemia vera (PV), 50%-70% of patients with essential thrombocythemia (ET), and 40%-50% of patients with primary myelofibrosis (PMF)." (PMID 27094255, 2016).
polycythemia vera (continued). "These alterations result from an abnormal signal transduction, secondary to mutations in genes encoding tyrosine kinase proteins or related molecules (BCR-ABL1 fusion gene in CML and JAK2 V617F mutation in polycythemia vera)." (PMID 26187587, 2015). "For example, the vast majority of Polycythemia vera patients carry gain-of function mutations in Janus kinase 2 (JAK2 V617F), while a hallmark of chronic myeloid leukemia (CML) is the generation of BCR-ABL fusion proteins." (PMID 26028666, 2015). "Impairment of the signaling pathway is also suspected in polycythemia vera (PV), an MP disorder associated with an acquired activated mutation of the tyrosin kinase JAK2." (PMID 22899948, 2012). "Somatic mutations of the JAK2 gene at V617F, which leads to constitutive JAK2 phosphorylation and kinase activation, occurs in almost all cases of polycythemia vera and approximately 50% of cases of chronic idiopathic myelofibrosis." (PMID 22028900, 2011). "A single-base somatic mutation in the gene of one of these kinases, Janus kinase 2 (JAK2), was reported to be responsible for autostimulation of the pathway, causing Epo-independent growth of erythroid cells in polycythemia vera." (PMID 21785724, 2011). "The JAK2 V617F mutation present in over 95% of Polycythemia Vera patients and in 50% of Essential Thrombocythemia and Primary Myelofibrosis patients renders the kinase constitutively active." (PMID 20585391, 2010). "In polycythemia vera (PV), an activating mutation in Janus kinase 2 (JAK2V617) induces splenomegaly and an increase in hematocrit." (PMID 19789710, 2009). "Recent studies have shown that polycythemia vera can be confirmed by the acquired somatic mutation JAK2 (V617F)." (PMID 19946506, 2009). "The JAK2 (V617F) point mutation test is sufficient for confirming the differential diagnosis of true polycythemia vera before surgery, and surgical intervention for angiomyolipoma should be evaluated cautiously." (PMID 19946506, 2009). "As in our patient, a positive JAK2 (V617F) point mutation can be proven as 'true' polycythemia vera with high specificity and sensitivity." (PMID 19946506, 2009). "According to the World Health Organization classification of MPNs, the primary MF, polycythemia vera (PV), and essential thrombocythemia (ET) are grouped as the Janus kinase 2 (JAK2) MPNs, with genetic mutations playing a distinctive role in their pathophysiology." (PMID 40640746, 2025). "Polycythemia vera is associated with an elevated risk of both arterial (e.g., myocardial infarction) and venous thrombotic events, driven by increased hematocrit, elevated blood viscosity, abnormal platelet activation, and JAK2 mutation-mediated inflammation." (PMID 40271338, 2025). "Common Philadelphia chromosome-negative MPNs, including polycythemia vera, essential thrombocythemia, and primary myelofibrosis (MF), frequently harbor the JAK2 V617F mutation, detected in ~95% of polycythemia vera and 50-60% of essential thrombocythemia and primary MF cases." (PMID 40605890, 2025). "Polycythemia Vera (PV) is typically caused by V617F or exon 12 JAK2 mutations." (PMID 38244120, 2024). "Since mutations in JAK2, such as JAK2 V617F, on chromosome 9p are known to cause polycythemia vera, we performed a multiple regression of age at time of blood draw, sex, and PACER score to predict erythrocyte counts for 11 individuals with CN-LOH or loss of chromosome 9p and erythrocyte count." (PMID 38714703, 2024). "It is well established that iron deficiency alters the polycythemia vera (PV) phenotype, but whether regulation of iron homeostasis modulates the pathophysiology of JAK2 V617F PV has been unclear." (PMID 36928379, 2023).
polycythemia vera (continued). "Moreover, the JAK2 V617 mutation has been found to be present in approximately 96% of patients with polycythemia vera, 50% of patients with primary thrombocytosis, and 60% of patients with primary myelofibrosis." (PMID 36671504, 2023). "The occurrence of JAK2 mutation was reported in nearly all patients with polycythaemia vera (PV)." (PMID 35631587, 2022). "Thrombotic events may occur in patients with polycythemia vera, and a JAK2 mutation further heightens that risk." (PMID 36458103, 2022). "JAK2-activating alterations may predict sensitivity to HDAC inhibitors; a phase I/II study of givinostat for patients with JAK2 V617F-mutated polycythemia vera reported ORRs from 72.7% (8/11, 1 CR) to 80.7% (25/31, 3 CRs) across trial arms." (PMID 36551764, 2022). "JAK2 mutations are present in most cases of polycythemia vera." (PMID 35237453, 2022). "Jak2 mediates EpoR signaling and is a causal gene of polycythemia vera." (PMID 33481887, 2021). "However, JAK2 mutation in patients with myeloproliferative neoplasms (polycythemia vera) caused overactivation of the PI3K and MAPK pathways." (PMID 34299300, 2021). "Polycythemia vera, especially with a positive JAK2 V617F mutation, may be a rare risk factor for CVT." (PMID 34134639, 2021). "Bone marrow biopsy confirmed JAK2-mutation-positive polycythaemia vera." (PMID 33505762, 2020). "In 2005, the discovery of the constitutively activating JAK2V617F mutation in the majority (97%) of patients with polycythemia vera (PV) and approximately 50% of patients with idiopathic myelofibrosis (MF) confirmed the central role played by JAK2 in the pathogenesis of myeloproliferative neoplasms." (PMID 31560729, 2019). "This was recently demonstrated for patients with JAK2 and TET2 double mutated polycythemia vera, where the individuals who had first acquired a JAK2 mutation had a higher risk of thrombosis and responded better to ruxolitinib than those who had first gained a TET2 mutation." (PMID 29740158, 2018). "Finally, a F136L germline SOCS3 mutation found in a subset of polycythemia vera patients has been shown to display an impaired capacity to inhibit erythropoietin receptor-JAK2 signalling." (PMID 29330478, 2018). "MPN, including polycythemia vera, essential thrombocythemia, and primary myelofibrosis are clonal diseases of hematopoietic progenitor cells associated with common mutations in the Janus kinase 2 (JAK2) gene, the gene encoding the thrombopoietin receptor (MPL), and the calreticulin (CALR) gene." (PMID 29143804, 2017). "This exploratory analysis from the multicenter, open-label, phase 3 Randomized Study of Efficacy and Safety in Polycythemia Vera With JAK Inhibitor INCB018424 Versus Best Supportive Care trial evaluated the long-term effect of ruxolitinib treatment on JAK2 p.V617F allele burden in patients with PV." (PMID 28456851, 2017). "This CpG island is known to be hypermethylated in lung and other cancers, but of particular interest to this blood tissue study, it was also found to be the only gene with promoter hypermethylation in a study of polycythaemia vera (PCV) JAK2 V617F mutation individuals." (PMID 27663977, 2016). "Polycythemia vera requires, in the majority of cases (95%), the negativity of Breakpoint cluster region-Abelson murine leukemia viral oncogene homolog 1 rearrangement and the presence of the Janus kinase 2 mutation." (PMID 26187587, 2015). "In detail, preferential expression of JAK2 mutant allele showed threefold increase from the cDNA compared with the genomic DNA from patients with essential thrombocythemia and twofold increase in polycythemia vera." (PMID 23349688, 2013). "Mutation of JAK2 is observed in several hematological disorders including ET, Polycythemia Vera, Primary Myelofibrosis and Acute Lymphoid Leukemia (ALL) as well as chromosomal translocations involving the fusion partners TEL, BCR, PCM1, PAX5, SEC 31A and SSBP2." (PMID 24086539, 2013).
polycythemia vera (continued). "Cytogenetically, patients with polycythemia vera may be heterozygous or homozygous for the JAK2 V617F mutation." (PMID 22028900, 2011). "Moreover, the recent discovery of Janus kinase 2 (JAK2) V617F mutation in most patients with polycythemia vera opens new avenues for the treatment of this disease." (PMID 19946506, 2009). "The recently discovered JAK2 V617F mutation which occurs in the majority of cases of polycythemia vera and in about half of the cases with the two other conditions, enables constitutive tyrosine kinase activity without the need for ligand binding to hematopoietic receptors." (PMID 17032464, 2006). "Similarly, JAK2 exon 12 mutations, including various insertions, deletions, and point mutations, although less common, result in persistent kinase activation and contribute to the development of polycythemia vera." (PMID 40140631, 2025). "We report the case of a 51-year-old male patient initially diagnosed with JAK2-V617F-mutated polycythemia vera (PV), who developed chronic phase BCR::ABL1-positive chronic myeloid leukemia (CML) 11 years later." (PMID 41137901, 2025). "Polycythemia vera (PV) is a hematopoietic stem cell neoplasm driven by somatic mutations in JAK2, leading to increased red blood cell (RBC) production uncoupled from mechanisms that regulate physiological erythropoiesis." (PMID 37095207, 2023). "Next-generation sequencing approaches to identify driver mutations have greatly enhanced our ability to identify JAK2 mutations in polycythemia (polycythemia vera [PV]) (Stuckey and Gómez-Casares, 2021)." (PMID 37428608, 2023). "The etiology may be related to polycythemia vera with Janus Kinase 2 V617F mutation." (PMID 34134639, 2021). "Likewise, at HMDS JAK2 mutations are used to diagnose chronic MPNs; but the further breakdown into polycythaemia vera (PV) and essential thrombocythaemia (ET) requires access to blood count data and other clinical parameters, and these procedures have only recently been routinely incorporated." (PMID 27090942, 2016). "Since the demonstration that the V617F mutation in the exon 14 of the JAK2 gene is present in about 90% of patients with Polycythemia Vera (PV), the detection of this mutation has become a key tool for the diagnosis of these patients." (PMID 20126644, 2010). "Conversely, genetic deletion of Osm in a JAK2 p.V617F-driven polycythemia vera mouse model reduced polycythemia, BM fibrosis, inflammatory cytokine levels and the expression of inhibitory markers on T cells." (PMID 41372120, 2025). "One of the differentially upregulated Stat5-target genes was Pim1, that is commonly found upregulated in JAK2-V617F polycythemia vera (PV) and other myeloid malignancies." (PMID 40841769, 2025). "This cluster was enriched with JAK2-mutated, JAK-inhibition naive MPN, mainly essential thrombocythemia and polycythemia vera with mild bone marrow fibrosis." (PMID 40764668, 2025). "Only a limited number of cases have demonstrated concurrent JAK2 and MPL mutations, which have been associated with myelodysplastic/MPNs, polycythemia vera, and essential thrombocythemia." (PMID 41439212, 2025). "He had been diagnosed with JAK2-positive polycythemia vera in 2014, a few months after his neurologic symptoms began." (PMID 40123933, 2025). "This case report explores the consequences of ruxolitinib via inhibition janus kinase 1 (JAK1) and JAK2 pathways in the context of fungal defense in a patient diagnosed with pulmonary coccidioidomycosis during ruxolitinib therapy for polycythemia vera." (PMID 41164159, 2025). "Polycythaemia vera (PV) is a myeloproliferative neoplasm attributed to genetic variation in JAK2 in > 97% of cases, usually by V617F and less commonly by exon 12 mutations." (PMID 37682452, 2024).
polycythemia vera (continued). "In human polycythemia vera RBC with the V617F mutant JAK2, there is an upregulation of Rap1-GTP expression, increased Akt activity, elevated phosphorylation levels of Lu/BCAM and enhanced RBC adhesion to laminin compared to wild-type JAK2." (PMID 39000374, 2024). "Homozygous JAK2 mutation (n = 40, 23%) was enriched with old patients with SMF after long-standing polycythemia vera, whereas MF with heterozygous JAK2 mutation (n = 22, 13%) was similarly distributed among PMF and SMF." (PMID 37568719, 2023). "Examples include sickle cell disease (HBB), essential thrombocytosis (JAK2), polycythemia rubra vera (JAK2), and hereditary thrombophilia (F2, F5)." (PMID 38132662, 2023). "We noted no major differences in germline susceptibility by type of MF, and observed a significant signal at 9p24.1 (JAK2) in post-polycythemia vera MF." (PMID 36075929, 2022). "The JAK2 V617F mutation is found in the majority of MPN patients including all three subtypes, such as in 95% of patients with polycythemia vera (PV) and 50–60% of patients with essential thrombocythemia (ET) or myelofibrosis (MF)." (PMID 35215273, 2022). "Our case is unique as there have not been any documented case reports of DIP with the use of hydroxyurea monotherapy for JAK2 polycythemia vera." (PMID 35891817, 2022). "According to studies, researchers have determined that most individuals with polycythemia vera have a variation in the JAK2 gene." (PMID 35456443, 2022). "JAK2 mutation, specifically V617F, is prevalent in classic (BCR-ABL negative) myeloproliferative neoplasms (MPNs) and is reported in up to 95% of polycythemia vera, 50–60% of essential thrombocythemia and 40–50% of primary myelofibrosis cases." (PMID 36551764, 2022). "Her JAK2 polycythemia vera treatment was switched from hydroxyurea to ruxolitinib 25 mg twice daily, which she has tolerated." (PMID 35891817, 2022). "We observed a strong genome-wide significant signal at 9p24.1 (JAK2) only in post-polycythemia vera MF, which is consistent with prior reports of higher JAK2 involvement in patients with polycythemia vera." (PMID 36075929, 2022). "JAK2 unmutated polycythaemia is frequent in clinical practice and is usually classified into polycythaemia vera (PV), secondary and hereditary polycythaemia." (PMID 35743463, 2022). "Mutations of Janus kinase 2 (JAK2), predominantly JAK2V617F, are discovered in ~95% of patients with polycythemia vera and 50–60% of patients with essential thrombocythemia, as well as primary myelofibrosis (MF)." (PMID 35256594, 2022). "JAK2 unmutated or non-polycythemia vera (PV) erythrocytosis encompasses both hereditary and acquired conditions." (PMID 34021251, 2021). "For example, isogenic iPSCs clones expressing JAK2-V617F mutant and wild type JAK2 were generated from polycythemia vera (PV) patients." (PMID 34685678, 2021). "JAK2V617F is detected in approximately 95% of polycythemia vera (PV) and 50–60% of essential thrombocythemia (ET) and primary myelofibrosis (PMF), whereas JAK2 exon 12 mutations are found exclusively in 2–3% of PV patients lacking the more common JAK2V617F." (PMID 34440731, 2021). "Twenty-three patients were categorized as polycythemia vera, JAK2 V617F was observed in 91.3% of these cases." (PMID 33936230, 2021). "The gain-of-function mutations in JAK2, i.e., mutation V617F, are often detected in patients with MPN, which includes polycythemia vera (PV), essential thrombocythemia (ET), and primary myelofibrosis (PMF)." (PMID 34502524, 2021). "For example, in KEGG, Polycythemia vera (disease gene: JAK2) is a cancer of haematopoietic and lymphoid tissues." (PMID 33126852, 2020). "Although BCR-ABL has robust transformation potential, JAK2 V617F-positive polycythemia vera (PV) is characterized by a long and stable latent phase." (PMID 32272770, 2020).